CDK4 (cyclin dependent kinase 4)
Diseases named in the same sentence as CDK4 in open-access papers (continued):
Sharing a sentence is not in itself a finding about the gene and the disease.
liposarcoma (continued). "In this study, using the currently available clinical grade genotyping panels in WD/DD liposarcoma, 20/20 (100%) patient samples tested had CDK4 amplified and 16/16 (100%) patient samples tested had MDM2 amplified." (PMID 29731991, 2018). "A recent study showed that the combination of IGF1R and CDK4 inhibitors synergistically reduced the cell proliferation of liposarcoma cells." (PMID 27893412, 2017). "Well-differentiated liposarcoma (WDLPS) and dedifferentiated liposarcoma (DDLPS) are closely related tumors commonly characterized by MDM2/CDK4 gene amplification, and lack clinically effective treatment options when inoperable." (PMID 28099935, 2017). "Ten of these co-amplified CDK4/MDM2 cases were dedifferentiated liposarcomas, seven were well-differentiated liposarcomas, two rhabdomyosarcomas (one pleomorphic and one nos), one osteosarcoma, one ewing sarcoma, and one unclassified soft tissue sarcoma." (PMID 28424409, 2017). "Clinical trials are underway in liposarcoma using MDM2 inhibitors either singly or in combination with CDK4 inhibitors." (PMID 28424409, 2017). "MDM2 and CDK4 have previously been proposed as tantalizing personalized targets in liposarcoma and indeed clinical trials are underway." (PMID 28424409, 2017). "MDM2 and CDK4 are frequently co-amplified in well-differentiated/dedifferentiated liposarcoma (WDLPS/DDLPS)." (PMID 28629371, 2017). "Recently, local amplification of the 12q13-15 regions, which contain copies of CDK4, was reported in well-differentiated liposarcoma." (PMID 27016421, 2016). "In a subset of liposarcomas the small subgroup of MDM2+/CDK4- tumors shows favorable prognostic features compared to MDM2+/CDK4+ tumors." (PMID 27662657, 2016). "Reports on the amplification of chromosome 12q13–15, containing oncogenes MDM2, HMGA2 and CDK4 in about 90% of well and dedifferentiated liposarcoma led to the development of new targeted agents." (PMID 26887042, 2016). "A recent clinical trial of Palbociclib, a selective CDK4 inhibitor, produced a favorable progression-free survival rate in liposarcoma." (PMID 26675259, 2016). "Efforts made to define the molecular basis of liposarcomas lead to the finding that besides the amplifications of CDK4 and MDM2, Aurora Kinase A, also was shown to be overexpressed." (PMID 26887042, 2016). "CDK4, a cytosolic kinase involved in cell cycle progression, is amplified in greater than 90% of liposarcoma cases." (PMID 26675259, 2016). "A phase II study demonstrated that the treatment of liposarcoma patients with palbociclib is associated with favorable PFS in tumors displaying pRb expression and CDK4 amplification." (PMID 26528855, 2015). "Analysis of IHC on a large number of sarcomas reported a sensitivity of 95 % and 92 % and a specificity of 81 % and 95 % for, respectively, MDM2 and CDK4 for the diagnosis of dedifferentiated liposarcoma." (PMID 26337721, 2015). "Recently, palbociclib has entered a phase II trial in patients with advanced CDK4-amplified or well differentiated liposarcoma." (PMID 26528855, 2015). "In summary, our data support the efficacy of CDK4 inhibitors for sarcomas displaying increased CDK4 expression in general, particularly liposarcomas." (PMID 26528855, 2015). "CDK4 gene amplification is commonly reported in atypical lipomatous tumors/well-differentiated liposarcomas, de-differentiated liposarcomas, and bone tumors." (PMID 26528855, 2015). "In fact, palbociclib has been tested in rabdomyosarcoma and liposarcoma harboring elevated CDK4 expression." (PMID 26528855, 2015). "Well-differentiated liposarcomas with higher level of amplification of CDK4 (≥7.54) were more likely to recur after surgical resection." (PMID 25121597, 2014). "As known, MDM2 and CDK4 immunohistochemistry or MDM2 FISH are useful in identifying dedifferentiated liposarcoma." (PMID 25432794, 2014).
liposarcoma (continued). "The results of a phase II trial of this drug recently presented show promising prospects for CDK4 inhibition in patients with progressed WD and DD liposarcoma." (PMID 25121597, 2014). "A Phase II trial in patients with advanced CDK4-amplified well-differentiated or dedifferentiated liposarcoma was also performed." (PMID 25349887, 2014). "Previous studies have reported positive immunoreactivity for CDK4 on IHC in approximately 68∼70% of liposarcomas." (PMID 25121597, 2014). "Immunohistochemical analysis of CDK4 has been shown to be helpful in the differential diagnosis of liposarcomas and benign lipomatous tumors." (PMID 25121597, 2014). "Q-PCR analysis of the liposarcomas revealed the presence of CDK4 amplification in 44 cases (91.7%) and MDM2 amplification in 46 cases (95.8%)." (PMID 25121597, 2014). "PCR analysis of the liposarcomas revealed the presence of CDK4 amplification in 44 cases (91.7%) and MDM2 amplification in 46 cases (95.8%)." (PMID 25121597, 2014). "Similar to MDM2, cyclin dependent kinase-4 or CDK4 is also consistently amplified in WD and DD liposarcoma and represents another appealing target for therapy for this histologic subtype." (PMID 24216990, 2013). "In view of this, a phase II study of this agent in CDK4-amplified, Rb-positive liposarcoma is now underway (ClinicalTrials.gov NCT01209598)." (PMID 21610706, 2011). "Furthermore, CDK4/6 inhibitors are inefficient in liposarcomas harbouring the amplification of CDK4/6 and murine double minute 2 (MDM2) genes." (PMID 38549846, 2024). "Therefore, the detection of CDK4/MDM2 by FISH or immunohistochemistry is necessary to exclude dedifferentiated liposarcoma." (PMID 38388450, 2024). "The expression of MDM2 and CDK4 genes in chromosome 12q13-15 was found to be amplified in both well-differentiated and dedifferentiated liposarcoma, and immunostaining showed high sensitivity and specificity in both tumors, which can be used for differential diagnosis." (PMID 39297994, 2024). "Around 10–20% of cases may show MDM2 and CDK4 amplification, which is typically found in dedifferentiated liposarcoma." (PMID 38982521, 2024). "In such cases, dedifferentiated liposarcoma might be a potential diagnosis due to the presence of MDM2/CDK4 amplification." (PMID 38275873, 2024). "Immunostaining for MDM2 and CDK4 is useful for the diagnosis of liposarcoma." (PMID 39297994, 2024). "Liposarcomas have a supernumerary ring and giant marker chromosomes, which are composed of amplified material from the long arm of chromosome 12 (q13-15), in which several oncogenes are located and leading to overexpression of CDK4." (PMID 37016649, 2023). "MDM2 and CDK4 amplification is also seen in other malignant tumors, such as dedifferentiated liposarcomas, among others, which may create a differential diagnostic challenge, given the morphological, immunohistochemical, and molecular similarities." (PMID 37108696, 2023). "In addition, well-differentiated and dedifferentiated liposarcomas (n = 10) were all characterized by MDM2/CDK4 co-amplification." (PMID 35053600, 2022). "LPS could also benefit greatly from a combination of CDK4/6 inhibition and immunotherapy due to the upregulation of CDK4 observed in the majority of well-differentiated liposarcoma (WDLPS) and DDLPS." (PMID 35327375, 2022). "For example, MDM2 amplification is present in most dedifferentiated liposarcomas and typically co-amplified with CDK4 and/or HMGA2, synovial sarcomas (SS) are often characterized by SS18–SSX fusions, and presence of MYOD1 mutations indicate spindle cell/sclerosing rhabdomyosarcoma." (PMID 35053600, 2022). "Recurrent alterations identified were often unique to specific sarcoma subtypes; CDK4/MDM2 amplifications were identified in all but one dedifferentiated liposarcoma, ASPSCR1-TFE3 fusions in all patients with alveolar soft part sarcoma, and fusions involving EWSR1 in all patients with SBRCT." (PMID 35710741, 2022).
liposarcoma (continued). "MDM2 and CDK4 are known to be amplified in well‐differentiated and dedifferentiated liposarcoma." (PMID 35586877, 2022). "More importantly, consistent MDM2 and/or CDK4 amplification is present in dedifferentiated liposarcomas, which is absent in USP6-associated soft tissue tumors with bone metaplasia." (PMID 36727055, 2022). "The mechanism of interaction between INSM1 and CDK4 may be involved in the development of liposarcoma, which needs to be further explored." (PMID 36531655, 2022). "Interestingly, MDM2 amplification and CDK4 polisomy have been observed in colorectal dedifferentiated liposarcomas." (PMID 35205133, 2022). "However, FISH analysis for the MDM2 and CDK4 gene amplification is usually helpful in distinguishing aggressive angiomyxoma from dedifferentiated liposarcoma." (PMID 33422117, 2021). "Interestingly, different from the prognosis value of CDK4 amplification in dedifferentiated liposarcoma and glioblastoma patients, we demonstrated that CDK4 amplification was associated with a better DFS (P = 0.016) and OS (P = 0.023)." (PMID 33995474, 2021). "CDK4 is commonly amplified, with a higher incidence (86%) in dedifferentiated liposarcoma." (PMID 34207243, 2021). "MDM2 and CDK4 were both positive in dedifferentiated liposarcoma cases used as controls." (PMID 32566457, 2020). "Likewise, MDM2 and CDK4 are both positive in dedifferentiated liposarcoma that can thus be distinguished from SFT." (PMID 32566457, 2020). "MDM2 and CDK4/6 are highly amplified in well-differentiated/dedifferentiated liposarcoma." (PMID 29510588, 2018). "For example, CDK4 is amplified in patients with well-differentiated liposarcoma and de-differentiated liposarcoma, hepatocyte growth factor receptor (MET) is overexpressed in de-differentiated liposarcoma, and SRC is activated in myxoid liposarcoma and pleomorphic liposarcoma." (PMID 29568347, 2018). "Furthermore, a high level of CDK4 amplification is a poor prognostic marker in well-differentiated and dedifferentiated liposarcoma." (PMID 29451912, 2018). "Concomitant alterations of MDM2 and CDK4 are known and have been described in liposarcoma." (PMID 30237864, 2018). "Targeting CDK4 is also an attractive option in WD/DD liposarcoma given its frequent overexpression." (PMID 29731991, 2018). "MDM2 and CDK4 (12q13-15 amplification) are co-amplified in well differentiated liposarcoma." (PMID 28424409, 2017). "Dedifferentiated/well-differentiated liposarcomas had a preponderance of MDM2 and CDK4 mutations." (PMID 28424409, 2017). "CDK4 is amplified in over 90% of well-differentiated and de-differentiated liposarcomas." (PMID 27074562, 2016). "For example liposarcoma which is the most common type of soft tissue sarcoma in adults, accounting for approximately 20% of all adult soft tissue sarcomas, is characterized by amplifications of CDK4 and MDM2." (PMID 26887042, 2016). "However, these profiles did not segregate by histology (lung adenocarcinoma-appendiceal cancer (KRAS G12D and GNAS R201C), and lung adenocarcinoma-liposarcoma (CDK4 and MDM2 amplification pairs))." (PMID 26418953, 2015). "Preclinical and clinical studies of liposarcoma suggested that the amplification of CDK4 may predict an increased response to CDK4 inhibitors." (PMID 26528855, 2015). "The overexpression of CDK4 was found to correspond to the gene amplification status and has been shown to be an especially useful marker for identifying well-differentiated and de-differentiated liposarcomas." (PMID 26528855, 2015). "However, among WD liposarcomas, CDK4 amplification was higher in the subgroup of cases which recurred after surgical resection compared to those without recurrence (P = 0.041, independent sample t-test)." (PMID 25121597, 2014). "It has been suggested that an absence of CDK4 amplification in WD and DD liposarcomas is associated with lower rate of recurrence and favorable prognosis." (PMID 25121597, 2014).
liposarcoma (continued). "In this study, we sought to identify factors associated with tumor recurrence and patient survival including the levels of MDM2 and CDK4 amplification in a homogeneous population of patients with WD and DD liposarcomas of the abdomen undergoing complete surgical resection." (PMID 25121597, 2014). "Our study adds further rationale to the current body of evidence that the use of CDK4 inhibitors in DD liposarcoma may prove to be beneficial." (PMID 25121597, 2014). "Utilization of Q-PCR for analysis of CDK4 amplification may aid clinicians in the postoperative surveillance and management of patients with abdominal WD and DD liposarcomas." (PMID 25121597, 2014). "Amplifications of genomic regions are not specific for a given sarcoma subtype, but amplification of the murine double minute gene (MDM2) and the cyclin-dependent kinase 4 (CDK4) at chromosome 12q13–15 are highly characteristic in dedifferentiated liposarcomas (LPS)." (PMID 22665999, 2012). "Furthermore, all dedifferentiated liposarcomas (DDLPSs), well-differentiated liposarcomas (WDLPSs), and atypical lipomatous tumors (ALTs) present chromothripsis in the long arm of chromosome 12, where amplified CDK4, HMGA2, and MDM2 genes are localized." (PMID 40141463, 2025). "However, it could be possible that they will have a potential to show the efficacy against sarcomas primarily driven by CDK4/6 deregulation such as dedifferentiated liposarcomas." (PMID 38434982, 2024). "In addition, well-differentiated liposarcoma and dedifferentiated liposarcoma are associated with amplifications in a specific region on chromosome 12 (12q13-15) that encompasses genes such as MDM2 and CDK4." (PMID 34440251, 2021). "The absence of CDK4 amplification in liposarcomas is associated with favorable prognosis." (PMID 25121597, 2014). "In addition, CDK4 has been shown to be amplified in patients with liposarcoma, which may explain the unusual degree of SD observed in this clinical trial." (PMID 21610706, 2011). "Interestingly, also the MFH/UPS, the leiomyosarcomas and the fibrosarcoma that clustered tightly with the dedifferentiated/pleomorphic liposarcomas showed amplification of CDK4 and MDM2 when analyzed by array comparative genomic hybridization (data not shown) or Southern blot analysis." (PMID 17359542, 2007). "Genetically, atypical lipomatous tumors/well-differentiated liposarcomas commonly exhibit amplification of the 12q13-q15 region, which encompasses the MDM2 and CDK4 genes." (PMID 40898472, 2025). "The amplification of several oncogenes, mainly CDK4, MDM2, and HMGA2, was involved in liposarcoma pathogenesis." (PMID 41531533, 2025). "The diagnosis of liposarcoma was further supported by positive immunohistochemical staining for MDM2 and CDK4, which are established markers of this neoplasm." (PMID 39974236, 2025). "Well-differentiated liposarcoma is characterized by variation in adipocyte size, atypical hyperchromatic nuclei of adipocytes and stromal cells, and up-regulation of MDM2 and/or CDK4." (PMID 40002892, 2025). "For instance, CDK4/CDK6 inhibitors (e.g., palbociclib) and MDM2 antagonists are under active investigation in clinical trials for advanced liposarcoma." (PMID 41488879, 2025). "Immunohistochemically, well-differentiated and dedifferentiated liposarcomas are positive for MDM2 and CDK4." (PMID 40002892, 2025). "Tumor cells do not express epithelial (CK), myogenic (desmin, SMA), neurogenic (CD56, NSE) markers, well-differentiated/dedifferentiated liposarcoma markers (MDM2, CDK4, p16), or solitary fibrous tumor (SFT) markers (β-catenin, STAT6)." (PMID 41458523, 2025). "The diagnosis of dedifferentiated liposarcoma was based on histology and MDM2 and/or CDK4 immunohistochemistry findings." (PMID 39839837, 2024).
liposarcoma (continued). "In these situations, the presence of well-differentiated liposarcoma, confirmed MDM2 and CDK4 expression by immunohistochemistry, or amplification by FISH would strongly support the diagnosis of dedifferentiated liposarcoma." (PMID 38388450, 2024). "In these particular cases, two patients initially diagnosed with leiomyosarcoma were reclassified as having dedifferentiated liposarcoma, leading to a change in their treatment approach to include investigational MDM2 or CDK4 inhibitors." (PMID 38228904, 2024). "A study of dedifferentiated liposarcoma found that high levels of MDM2 amplification (>38 copies) and CDK4 amplification (>30 copies) were correlated with reduced disease-free survival (DFS) and disease-specific survival (DSS)." (PMID 38275873, 2024). "This case initially suggested dedifferentiated liposarcoma with smooth muscle differentiation due to strong MDM2 and CDK4 positivity." (PMID 38993816, 2024). "Advances in molecular biology offer promising avenues for personalized therapy, with potential targets such as CDK4 and MDM2 in well-differentiated and dedifferentiated liposarcomas." (PMID 39347341, 2024). "In recent years, specific inhibitors of CDK4/6 and MDM2 and VEGFR/FGFR/PDGFR multi-kinase inhibitors have been proposed for the treatment of liposarcoma." (PMID 38254762, 2024). "Regarding the CDK4 status, we identified the majority of cases with a positive immunoreaction in ALT/WDLS (93.75%), followed by liposarcoma (70.59%) and lipoma (7.59%) (p < 0.001)." (PMID 38132190, 2023). "The final histopathology diagnosis was a grade 3 dedifferentiated liposarcoma (FNCLCC), with certain response to radiotherapy and positive MDM2, CDK4 markers." (PMID 37888062, 2023). "This assumption is supported by the fact that patients with dedifferentiated liposarcoma characteristically carry MDM2 (and CDK4/6) amplifications and novel MDM2 inhibitors are tested in the first-line setting (NCT05218499)." (PMID 37542550, 2023). "In fact, liposarcomas are defined by amplification of MDM2, which is frequently co-amplified with its genomic neighbor CDK4/6." (PMID 36980578, 2023). "Amplification of CDK4 and murine double minute 2 (MDM2) is observed in 90% of dedifferentiated liposarcoma, suggesting the usefulness of palbociclib." (PMID 36003796, 2022). "Several molecular targeted therapies exist for other subtypes, including CDK4 inhibitors and MDM2 inhibitors for well-differentiated liposarcoma and dedifferentiated liposarcoma, and trabectedin for myxoid liposarcoma." (PMID 34797454, 2021). "Murine double minute 2 (MDM2) and cyclin-dependent kinase 4 (CDK4) are both coded on chromosome 12q13-15 and are known to be amplified in well-differentiated and dedifferentiated liposarcoma." (PMID 31963219, 2020). "Dedifferentiated liposarcomas have genetic abnormalities with high-level amplification of chromosome 12q14–15, which includes the MDM2 and CDK4 cell cycle oncogenes." (PMID 32611426, 2020).